C3 (complement C3)
Diseases named in the same sentence as C3 in open-access papers (continued):
Sharing a sentence is not in itself a finding about the gene and the disease.
ischemic stroke (continued). "However, increased C3 levels in ischemic stroke patients have previously been reported." (PMID 32466277, 2020). "Thus, C3 has a dual role during the pathogenesis of ischemic stroke." (PMID 31011487, 2019). "In addition, deficiency in C3, a central protein of all complement pathways, provides effective protection in the acute phase, but not the subacute phase following ischemic stroke." (PMID 26714866, 2015). "Thus, studies have demonstrated that a panel of biomarkers, including complement C3, high-sensitive C-reactive protein, hepatocyte growth factor, MMP9, and anti-phosphatidylserine antibodies, can provide more comprehensive risk stratification for adverse outcomes in ischemic stroke." (PMID 39459548, 2024). "In experimental ischemic stroke, pretreatment with CVF could inhibit complement activation by removing circulating C3 and other complement components, exerting beneficial effects on the outcomes of ischemic brain injury." (PMID 31011487, 2019). "In conclusion, our data show that plasma C3 and C3a are elevated in CE and SVD stroke but the dynamics of this increase as well as the potential prognostic value of these markers is influenced by ischemic stroke etiology." (PMID 23977229, 2013). "Previous studies have reported the vital role of complement C3 in brain injury after experimental ICH and ischaemic stroke, but the role of C3 in hemorrhagic stroke has not been determined." (PMID 38532579, 2024).
cognitive decline (26 papers, 2014 to 2026). "Overall, germline C3-deficiency resulted in a sparing of age-related cognitive decline when compared to C3-sufficient WT mice." (PMID 40678242, 2025). "Another report has shown that C3 and C3aR are positively associated with cognitive decline in the brains of AD patients." (PMID 38255891, 2024). "Another cohort study employing the Luminex assay has reported a similar association of low levels of CSF C3 with faster cognitive decline." (PMID 38238858, 2024). "Whereas therapeutic studies have implicated C3 opsonization of neurons and synapses in driving secondary injury and cognitive decline in both acute and chronic phases after TBI, the role of complement receptors has not been specifically investigated in TBI." (PMID 34281628, 2021). "C3 deficiency has been demonstrated to increase the Aβ plaque load while it is protective against age- and AD-related synaptic loss and cognitive decline by altering the glial response within the Aβ plaques." (PMID 30743990, 2019). "Furthermore, another group showed that overexpression of C5a caused a cognitive decline in mice and increased the levels of complement components (e.g., C3) in the Arctic model of AD." (PMID 38255891, 2024). "It has been shown that during the aging process, the progressive accumulation of complement C1q and C3 in the hippocampus promotes cognitive decline and memory impairments." (PMID 37177836, 2023). "C3/C3aR activation can induce impairments in blood-cerebrospinal fluid barrier (BCSFB) in the choroid plexus, which has been implicated in cognitive decline." (PMID 30180861, 2018). "In summary, our data suggest that CSF C3 and FH levels are prognostic biomarkers of accelerated cognitive decline in MCI, although validation in an independent cohort is needed." (PMID 25478014, 2014). "Notably, the expression of C3 and C3aR1 positively correlates with cognitive decline and further increases with progression of disease in the hippocampus of PS19 mice." (PMID 40641620, 2025). "With progressive cognitive decline, there is a decrease in plasma C3 protein levels." (PMID 37685872, 2023). "For instance, surgical trauma could activate the hippocampal complement C3, causing a decrease in the expression of pre- and post-synaptic proteins SYP and PSD-95, which contributed to cognitive decline." (PMID 35370607, 2022). "Complement cascade, specially C3/C3aR signaling activation, underlies several neurological conditions featuring CNS inflammation, synapse dysfunction, choroidal BCSFB permeability changes, and cognitive decline in different models of neurological disorders." (PMID 30180861, 2018). "Because CSF amyloid and tau biomarker levels are associated with differences in longitudinal cognitive functions, we hypothesized that classification using CSF C3 and FH levels can enhance the prediction of longitudinal cognitive decline." (PMID 26887322, 2016). "Our lab has previously shown that complement activation promotes neurodegeneration and cognitive decline after TBI, and that C3 activation represents a potential therapeutic target for treating TBI." (PMID 38632569, 2024). "First, our finding of low levels of CSF C3 and FH in MCI patients with accelerated cognitive decline may reflect increased deposition of these complement biomarkers in senile plaques." (PMID 25478014, 2014). "Complement C3 levels correlated positively with indicators of motor dysfunction (H&Y stage and UPDRS)—indicating a direct connection between high plasma levels of inflammatory proteins and motor symptoms—and negatively with cognitive decline, here with the MMSE." (PMID 38890280, 2024).
myocardial infarction (26 papers, 2008 to 2025). Gross necrosis of the myocardium, as a result of interruption of the blood supply to the area, as in coronary thrombosis. "Middle-aged males with high C3 serum levels were found to be at an increased risk for myocardial infarction, while high C3 levels in women were linked to atherosclerotic problems." (PMID 35955822, 2022). "Complement C3 is also associated with myocardial infarction, and it is more significant than any other traditional risk factors." (PMID 24363825, 2013). "Mice deficient for either C3 or the membrane receptor for C3a (C3aR) is protected against chronic left ventricular remodeling after myocardial infarction (own unpublished results)." (PMID 23740214, 2013). "Dysregulated platelet-neutrophil communication and surplus of C3 and NETs are predictors of acute myocardial infarction and myocardial infarct size and are therefore believed to increase the risk of influenza-associated myocardial infarct." (PMID 35419008, 2022). "For instance, in the model of experimental myocardial infarction (MI) mentioned, ptx3-deficient mice had greater myocardial lesions, more leukocyte infiltration, more cell death and higher complement C3 deposition in the infarcted area." (PMID 31057548, 2019). "Endogenous production of complement components following myocardial infarction has been shown, and C3 and CFD have been shown to play a role in cardiac remodeling in right heart failure in mice, where C3 and CFD deletion ameliorated heart failure." (PMID 38527066, 2024). "She ultimately died from acute myocardial infarction while awaiting results of direct immunofluorescence, which revealed the deposition of immunoglobulin (Ig) M, IgG, and C3 along the basement membrane, thus enabling a diagnosis of SLE." (PMID 36895547, 2023). "In a case-control study, the serum levels of C3 and C4 were significantly increased in acute myocardial infarction patients and stable angina patients compared with controls." (PMID 31829184, 2019). "Experimental and clinical studies strongly implicate the complement system as pivotal in IRI8,10,11,29 and therapeutic depletion or inhibition of complement at the level of C3 or C5 has been found to reduce myocardial infarct size in different animal models." (PMID 29170426, 2017). "Interventions inhibiting complement activation, especially the central component C3/C3a may represent a novel target for prevention and treatment of chronic heart failure after large myocardial infarction." (PMID 23740214, 2013). "Individually, elevated levels of complement C3 and coronary NET burden are predictors of acute MI and myocardial infarct size, respectively." (PMID 30992428, 2019).
malaria (25 papers, 2005 to 2026). Malaria is a serious and sometimes fatal disease caused by a parasite that commonly infects a certain type of mosquito which feeds on humans. "In malaria, the complement system has been highlighted as a complex of soluble, heat-sensitive, and cell surface-associated proteins that participate in pathogen opsonization, pathogen lysis, and recruitment of phagocytes via downstream C3 complement deposition." (PMID 37628675, 2023). "TEP1 is a homolog of the mammalian C3 complement factor secreted in the hemolymph where it can bind to malaria parasites, leading to their elimination through lysis and melanization." (PMID 32105779, 2020). "Consistent with complement-fixation to CSP, we observed greater C1q and C3-fixation in the presence of antibodies from the PNG individual than the malaria-naïve individual." (PMID 29706136, 2018). "To explore this further, we randomly selected serum samples (n = 10) from children (>24 months old) to examine levels of complement C3 and C5b-9 deposition during malaria." (PMID 28515136, 2017). "We recommend further investigations into the contribution of reduced C3 levels during the acute phase of malaria to poor NRBA and WBBA with respect to S. Typhimurium, an aspect that was not explored in our current study." (PMID 28515136, 2017). "Taken together, the data suggest a transient increase in consumption of the C3 complement component during acute malaria which rebounded to levels comparable to those seen with nonmalarial children by day 14 of malaria convalescence." (PMID 28515136, 2017). "It was observed that the levels of Complement C3 and Complement C4-B, Complement C5, Complement C9, Complement factor B and Complement C1q subcomponent subunit C were significantly elevated in malaria plasma MPs compared to controls." (PMID 28352210, 2016). "Depressed levels of C3 were found in severe and uncomplicated malaria as compared to healthy controls." (PMID 24804253, 2014). "Previous studies have shown that complement components C1q, C4, C3 and C5a change in malaria patients." (PMID 22028888, 2011). "In the present study, the dynamics of complement factors C1q, C3 and C5 in the brains and sera of mice with malaria were investigated." (PMID 18847493, 2008). "Our hypothesis is that the covalent deposition of C3 activation fragments on or close to CCP CR1 and DAF on E constitutes the most important mechanism for loss of np‐E in malaria." (PMID 41230021, 2025). "Finally, malaria can activate complement through C3-independent pathways through cleavage of C3 and C5 via thrombin and serine proteases released by phagocytic leukocytes or the parasite." (PMID 26733992, 2015). "Complement system components like C1q, C3, C4, and C5a are affected in malaria patients." (PMID 24804253, 2014). "Furthermore, depletion of complement C3 was reported in severe and uncomplicated malaria patients as compared to healthy controls." (PMID 22028888, 2011). "It is noteworthy that some C3-fixation was observed in the presence of malaria-naïve antibodies, suggesting that C3 may bind directly to the sporozoite surface to some extent, although this was substantially lower than C3-fixation in the presence of malaria-exposed antibodies." (PMID 29706136, 2018). "These investigators found that circulating E taken from children with malaria had low levels of CR1, and of decay accelerating factor (DAF), and C3 activation fragments could also be demonstrated on the E." (PMID 41230021, 2025). "Trophozoite stage pRBCs of the placental binding P. falciparum isolate CS2 were opsonized with antibodies from 302 PNG women or 15 malaria non-exposed Australian donors and tested for their ability to fix complement factors C1q or C3 by flow cytometry." (PMID 34425801, 2021). "Some C3 fixation on pRBCs was detected when using malaria non-exposed antibodies or unopsonized controls, but levels were much lower than those seen with the PNG antibodies pool." (PMID 34425801, 2021).
malaria (continued). "Whether np‐E in which the C3 fragments have been degraded to C3d are also removed from the bloodstream in malaria is not clear." (PMID 41230021, 2025). "Genome-wide expression analyses showed an upregulation of C1q, C3, C5aR, and C3aR genes in the placentas of primigravid women with malaria compared to placentas of primigravid women without placental malaria, implying a role for classical complement activation in disease pathology." (PMID 34168652, 2021). "C3 fixation on DBL5, tested for a subset of 35 randomly selected PNG antibody samples, was also significantly higher compared to malaria non-exposed donor samples (n=10) (P<0.001) and strongly correlated with C1q fixation (Spearman r=0.89, P<0.001)." (PMID 34425801, 2021). "In relation to SBA, C3 deposition on S. Typhimurium was significantly reduced in febrile P. falciparum-infected children (median, 7.5% [IQR, 4.1, 15.0]) compared to nonfebrile malaria-negative children (median, 29% [IQR, 11.8, 48.0], P = 0.048)." (PMID 28515136, 2017).
C3 glomerulonephritis (24 papers, 2014 to 2026). "C3NeF stabilizes C3 convertase, sustains C3 activation, and causes C3 glomerulonephritis (C3GN)." (PMID 37452997, 2024). "Of note, based on electron microscopic findings, type II MPGN forms a continuum with C3 glomerulonephritis, which is characterized by amorphous C3 deposition within the capillary wall and mesangium." (PMID 39309006, 2024). "C3 glomerulonephritis was more evident in gold-labeled electron microscopy, which further clarified the localization of C3 deposition." (PMID 37363300, 2023). "C3 glomerulonephritis (C3GN) is characterised by an abnormal deposition of complement C3 in the glomeruli due to abnormal activation of the alternative pathway of the complement system." (PMID 33482806, 2021). "Electron microscopy demonstrated all C3 glomerulonephritis patients had C3 deposition (100% vs 38% p = 0.02), these deposits were amorphous in nature (50% vs 5% respectively p = 0.007)." (PMID 32652953, 2020). "Renal pathological demonstrated the diagnosis of C3 glomerulonephritis (C3GN) showing mesangial proliferative glomerulonephritis with C3 staining only, effacement of podocyte process and intramembranous electron dense deposit by electric microscopy." (PMID 32725812, 2020). "C3 glomerulonephritis (C3 GN) is a recently defined entity characterized by predominant C3 deposition in glomeruli due to abnormal activation of the alternative pathway of complement system." (PMID 27631242, 2016). "Among the non-sclerotic glomeruli, several demonstrated diffuse granular mesangial staining for C3, while other glomeruli had small crescents, consistent with a mixed picture of C3 glomerulonephritis (C3GN) and crescentic glomerulonephritis." (PMID 27004158, 2016). "Renal histology revealed diffuse endocapillary proliferative glomerulonephritis with complement 3- (C3-) dominant staining and subendothelial electron dense deposit, mimicking C3 glomerulonephritis." (PMID 25506445, 2014). "Yet another mimic is C3 glomerulonephritis (C3GN), which shares C3-predominant staining with minimal Ig deposition on IF-F." (PMID 40851714, 2025). "The patients were divided into two groups: the first group consisted of patients with MPGN type 1 and C3 deposition (n=13), and the second group comprised patients with C3 glomerulonephritis with non-MPGN C3 deposition (n=6)." (PMID 27460033, 2016). "The immunohistologic diagnosis of C3 glomerulonephritis is made based on the presence of mesangial C3 deposition together with the absence of immunoglobulin and other complement components." (PMID 27460033, 2016). "Although isolated C3 positivity without IgG, IgM, IgA, or C1q is a diagnostic criterion for C3 glomerulonephritis (C3GN), the patient’s history of MRSA endocarditis and complete recovery with antibiotic therapy support a diagnosis of C3-dominant endocarditis-associated GN." (PMID 41230477, 2025). "C3 deposition in the absence of immune complex deposits can be seen in patients with IRGN, but with the emergence of C3 glomerulonephritis (C3GN), the distinction is difficult as the clinical and pathological presentation may be similar." (PMID 32140372, 2020).
liver fibrosis (24 papers, 2011 to 2025). "In a proteomic survey of serum samples from HCV-infected patients, liver fibrosis stage was associated with a decrease in C3, C4, and Factor H-related protein-1, a regulatory C3b-binding protein." (PMID 29910796, 2018). "The Pro-C3 protein fragment provided clinically relevant diagnostic accuracy as a single marker of liver fibrosis." (PMID 26406331, 2015). "Our results support Pro-C3 as an important candidate biomarker for non-invasive assessment of liver fibrosis in NAFLD." (PMID 34944736, 2021). "In C3aR−/− mice model, we also demonstrated that C3aR depletion significantly reduced the progression of NASH related liver fibrosis.Studies have confirmed that C3a is an important derivative produced by C3 cleavage when complement system is activated." (PMID 34395461, 2021). "The ability of exercise to prevent the histological progression of fibrosis was confirmed by the changes in circulating markers of hepatic fibrosis, namely, Pro-C3, Pro-C4, and C6M." (PMID 32486073, 2020). "Although more detailed studies of the role of IgM and C3 in muscle regeneration and fibrosis are necessary, C3 has already been shown to influence the development of liver fibrosis in other animal models." (PMID 21798099, 2011). "However, using direct non-invasive fibrosis tests (e.g., pro-C3 or enhanced liver fibrosis test (ELF)) might be a valuable addition to further cross-validate our findings." (PMID 36615054, 2022). "Administration of efruxifermin for 16-weeks significantly reduced liver fat and fibrosis markers including the enhanced liver fibrosis (ELF) scores and pro-C3 in a phase 2a trial." (PMID 40492139, 2025). "In people with compensated or decompensated cirrhosis, 28 weeks of survodutide treatment led to a trend of decreasing markers of liver fibrosis including liver stiffness, ELF scores, and plasma Pro-C3." (PMID 40492139, 2025). "At baseline, mean alanine aminotransferase (ALT), aspartate aminotransferase (AST), fibrosis-4 (FIB-4) index, Enhanced Liver Fibrosis (ELF) score, cytokeratin-18 (K-18) and serum pro-peptide collagen III (pro-C3) were normal or modestly elevated." (PMID 38858523, 2024). "Among the previously suggested serum biomarkers of liver fibrosis and collagen formation (Pro-C3, Pro-C4, and Pro-C6), only Pro-C4 and Pro-C6 but not Pro-C3 were elevated in CVID patients with portal hypertension." (PMID 35821451, 2022).